LBR (lamin B receptor)
Description:
Catalyzes the reduction of the C14-unsaturated bond of lanosterol, as part of the metabolic pathway leading to cholesterol biosynthesis. Plays a critical role in myeloid cell cholesterol biosynthesis which is essential to both myeloid cell growth and functional maturation (By similarity). Mediates the activation of NADPH oxidases, perhaps by maintaining critical levels of cholesterol required for membrane lipid raft formation during neutrophil differentiation (By similarity). Anchors the lamina and the heterochromatin to the inner nuclear membrane.
Synonyms: C14SR; DHCR14B; TDRD18; LMN2R; PHA; PHASK
Tractability: Antibody: UniProt predicts a signal peptide or a membrane-spanning region. PROTAC: ubiquitination databases record sites on it; its protein half-life has been measured.
Target class: Enzyme; Oxidoreductase
Gene: Protein-coding gene on chromosome 1 (225,400,900 to 225,428,925, reverse strand). Ensembl gene ENSG00000143815.
Subcellular location: Nucleus inner membrane; Endoplasmic reticulum membrane; Cytoplasm; Nucleus
Subcellular location (Human Protein Atlas): Nuclear membrane; Nucleoli fibrillar center
Pathways (Reactome):
Signal Transduction: CDC42 GTPase cycle; RAC1 GTPase cycle; RAC2 GTPase cycle; RAC3 GTPase cycle; RHOA GTPase cycle; RHOC GTPase cycle; RHOD GTPase cycle; RHOG GTPase cycle
Cell Cycle: Initiation of Nuclear Envelope (NE) Reformation
Metabolism: Cholesterol biosynthesis via desmosterol (Bloch pathway)
Gene Ontology:
Molecular function: chromo shadow domain binding; Delta14-sterol reductase activity; NADPH binding; protein binding; RNA binding; DNA binding; lamin binding; chromatin-protein adaptor activity; oxidoreductase activity, acting on the CH-CH group of donors, NAD or NADP as acceptor
Biological process: cholesterol biosynthetic process; neutrophil differentiation; random inactivation of X chromosome; sterol biosynthetic process; zymosterol biosynthetic process
Cellular component: cytoplasm; endoplasmic reticulum membrane; membrane; nuclear inner membrane; nuclear membrane; nucleus; nuclear envelope; nuclear lamina
Genetic constraint (gnomAD): Loss-of-function variants: 25 observed, 70.02 expected, observed/expected ratio (o/e) 0.36, 90% interval 0.26 to 0.5. The synonymous counts are far from expectation, so gnomAD's model fits this gene poorly and the ratio says little. Missense variants: 680 observed, 751.24 expected, observed/expected ratio (o/e) 0.91, 90% interval 0.85 to 0.96. Synonymous variants: 215 observed, 269.85 expected, observed/expected ratio (o/e) 0.8, 90% interval 0.71 to 0.89.
Gene-disease validity (ClinGen):
ClinGen rates the evidence that LBR causes each of these diseases.
Greenberg dysplasia (autosomal recessive): Moderate. A very rare lethal skeletal dysplasia characterized by fetal hydrops, short limbs and abnormal chondro-osseous calcification.
regressive spondylometaphyseal dysplasia (autosomal recessive): Moderate.
Homologues: Orthologues: chimpanzee LBR (99% identical), macaque LBR (98% identical), pig LBR (86% identical), rabbit LBR (84% identical), dog LBR (82% identical), rat Lbr (80% identical), mouse Lbr (80% identical), zebrafish lbr (53% identical), tropical clawed frog lbr (48% identical). Paralogues in human: TM7SF2 (39% identical), DHCR7 (25% identical).
Diseases named in the same sentence as LBR in open-access papers:
LBR is named in the same sentence as 47 diseases in open-access papers, as found by Europe PMC text mining. Sharing a sentence is not in itself a finding about the gene and the disease. The quoted sentences say what the papers report.
laminopathies (8 papers, 2010 to 2025). "The PHA is a blood laminopathy associated with mutations in the lamin B receptor (LBR) gene, and the characteristic of it is bi-lobed nuclei of leukocytes with symmetrical “dumbbell” or “pince-nez” appearance that is connected by a thin filament of chromatin." (PMID 38558935, 2024). "Owing to the dual functions of the LBR protein, which acts as both a receptor for lamin B and an enzyme of the cholesterol biosynthesis pathway, LBR-linked diseases are currently classified as laminopathies as well as disorders of cholesterol biosynthesis." (PMID 30518689, 2018). "Another example are the laminopathies caused by mutations in nuclear lamins (LMNA) and the lamin B receptor (LBR) genes." (PMID 34422840, 2021). "Laminopathies comprise more than 15 different phenotypes, as the Hutchinson–Gilford progeria syndrome or the Greenberg dysplasia, arising due to mutations in lamin A (LMNA) and lamin B receptor (LBR) coding genes, respectively." (PMID 40282211, 2025).
breast carcinoma (7 papers, 2019 to 2024). "Our data are further in accordance to previously published manuscripts as both molecules, the LBR and LMNB1, are mentioned in association with cellular senescence and ageing in different cancer types like PC, breast cancer, HCC and adenocarcinoma." (PMID 35883595, 2022). "We used human mammary carcinoma and osteosarcoma cell lines, both original and shRNA knockdown clones targeting lamin B receptor (LBR) and leading to LBR and lamin B (LB1) reduction." (PMID 32316379, 2020). "Similarly, abilities of conditioned medium from CAFs to promote breast cancer proliferation, migration and invasion was inhibited by reduced miR-222 levels or by LBR overexpression." (PMID 31481734, 2019). "In conclusion, we present miR-222 and LBR as key molecules involved in transformation and maintenance of breast CAFs, which in turn therefore impacts on the aggressive tumorigenic behaviour of breast cancer cells." (PMID 31481734, 2019). "miR-222 overexpression, or LBR knockdown, was sufficient to induce NFs displaying enhanced migration, invasion, and senescence characteristic of CAFs, and in addition, conditioned mediators from these fibroblasts induced an increase in breast cancer cell migration and invasion." (PMID 39090094, 2024). "We concluded that upregulation of miR-222 and downregulation of LBR were both necessary and sufficient for CAF function with respect to inducing proliferation of breast cancer cells." (PMID 31481734, 2019). "Likewise, in breast cancer, tumor-derived nicotinamide phosphoribosyltransferase (NAMPT) is involved in the generation of NAD+, thus supporting the NAD+-dependent deacetylation that regulates the transcription of lamin B receptor (LBR)." (PMID 38023616, 2023).
Greenberg dysplasia (7 papers, 2013 to 2025). "This may explain why truncated forms of LBR that are degraded, and/or LBR mutants that result in complete loss of its sterol reductase activity, are associated with Greenberg dysplasia and are lethal in humans." (PMID 28858257, 2017). "At the severe end, biallelic loss-of-function mutations of LBR fatally disrupt skeletal development, resulting in the clearly recognizable clinical entity of hydrops-ectopic-calcification-moth-eaten (HEM), also known as Greenberg dysplasia (GRBGD, MIM 215140)." (PMID 30518689, 2018). "For example, homozygosity for mutations R583Q (that leads to the production of full-length LBR lacking sterol reductase activity) and c.32delTGGT (that creates a premature stop codon) cause Greenberg dysplasia." (PMID 28858257, 2017). "Mutations within the transmembrane segments result in defects in cholesterol synthesis and are associated with diseases such as the Pelger–Huët anomaly and Greenberg skeletal dysplasia, whereas no such harmful mutations related to the anchoring properties of LBR have been reported so far." (PMID 28858257, 2017).
Pelger-Huët anomaly (7 papers, 2005 to 2022). "Mutations in LBR have been found to segregate with Pelger-Huët anomaly in an autosomal dominant fashion in linkage studies." (PMID 35650273, 2022). "TM7SF2 is a paralog of the well-characterized NET lamin B-receptor (LBR) that has been linked to the human disorders Pelger-Huet anomaly and Greenberg skeletal dysplasia." (PMID 33330474, 2020). "LBR mutant derivatives implicated in Greenberg skeletal dysplasia or Pelger-Huët anomaly fail to rescue the cholesterol auxotrophy of a LBR-deficient human cell line, consistent with a loss-of-function mechanism for these congenital disorders." (PMID 27336722, 2016). "Using a human cell culture model, we demonstrate that it is this function that is perturbed by LBR mutations associated with Pelger-Huët anomaly and Greenberg skeletal dysplasia, suggesting a loss-of-function mechanism for these congenital disorders." (PMID 27336722, 2016). "Two congenital disorders are known to be associated with mutations in LBR: Pelger-Huët anomaly and Greenberg skeletal dysplasia." (PMID 27336722, 2016). "We have shown NE deficiency of LBR in human Pelger Huet anomaly and mouse ichthyosis, resulting in granulocyte nuclear hypolobulation." (PMID 16287503, 2005). "The same is true for patients suffering from Pelger-Huet anomaly (PHA), a mutation in the human LBR leading to hyposegmentation of the neutrophil nucleus." (PMID 30505310, 2018). "In a heterozygous state, some, but not all, LBR mutations cause Pelger-Huët anomaly (PHA, MIM 169400), a benign condition just marked by the hypolobulation of granulocyte nuclei." (PMID 30518689, 2018).
ichthyosis (5 papers, 2004 to 2017). Disorders of cornification that are characterized by visible scaling and/or hyperkeratosis of most or all of the skin. "LBR mutations cause the human Pelger–Huët anomaly, the human Greenberg skeletal dysplasia which is lethal and ichthyosis in mice." (PMID 28858257, 2017). "The human PHA disease caused by mutation in the Lamin B receptor (LBR) gene is modeled by the ichthyosis (ic) mice." (PMID 19849840, 2009). "The suspected role of LBR was confirmed in subsequent studies, which demonstrated that a genetic deficiency of LBR correlates with hypolobulated granulocyte nuclei in the human Pelger-Huet anomaly and the murine Ichthyosis mutation." (PMID 15317658, 2004). "The pivotal role of LBR in determining granulocytic nuclear lobulation was demonstrated with the human Pelger-Huet anomaly and murine Ichthyosis mutations." (PMID 15317658, 2004). "By contrast, in homozygous ichthyosis mice that lack LBR, TM7SF2 seems to be inadequate to compensate for the LBR deficiency." (PMID 28858257, 2017). "These knockdown cells provide an in vitro model for genetic disorders such as the Pelger–Huët anomaly in humans and ichthyosis in mice, both of which are caused by mutations in the LBR gene leading to a complete or partial lack of functional LBR." (PMID 28858257, 2017).
melanoma (3 papers, 2022 to 2026). A malignant, usually aggressive tumor composed of atypical, neoplastic melanocytes. "Use of tumor organoids and an in vivo melanoma model revealed that upregulation of LBR was associated with increased NE fragility, metastatic invasion, and decreased patient survival." (PMID 41706894, 2026). "Summing it up, LBR downregulation in melanoma might cause an upregulation of several genes involved in translational processes, resulting in ER stress and affecting mitotic processes, eventually leading to the functional results we determined." (PMID 35883595, 2022). "Thus, upregulation of LBR in melanoma promotes nuclear deformability, while LBR's sterol reductase activity causes fragility and instability of the nuclear membrane, and these changes in the nucleus provide a possible mechanism for increased genetic heterogeneity in melanomas." (PMID 41706894, 2026). "LMNB1 and the LBR are functionally relevant for melanoma cells to prevent them from cell cycle arrest through influencing the regulation of several genes." (PMID 35883595, 2022). "The connection between LMNB1 and LBR upregulation in melanoma and changes in chromatin organisation or stability described in this study were not shown before." (PMID 35883595, 2022). "In this study, we revealed that LMNB1 and the LBR are higher expressed in melanoma compared to normal human epidermal melanocytes (NHEMs)." (PMID 35883595, 2022). "To get more information about the molecular and functional role of the LBR in malignant melanoma, we performed RNA-Seq (PRJNA841450) of the siLBR-transfected MEL-JUSO cells and the corresponding control cells." (PMID 35883595, 2022). "Our findings suggest that LMNB1 and LBR influence senescence and affect nuclear processes like chromatin condensation and thus are functionally relevant for melanoma progression." (PMID 35883595, 2022). "Changes in the expression of lamins have been linked to various tumour entities; however, the relationship appears to be complex, and less is known about the role of LMNB1 and the LBR in melanoma." (PMID 35883595, 2022). "As proof of concept, the increased amount of heterochromatin foci in long-term-transfected melanoma cells further supports the functional effect of LBR knockdown leading to senescence." (PMID 35883595, 2022). "Due to the newly detected upregulation of the LBR in melanoma cells, we also wanted to identify the functional relevance of this change in gene expression." (PMID 35883595, 2022). "Meta-analysis of transcriptomic data from clinical samples of melanoma progression together with an siRNA-based live-cell confinement screen revealed that lamin B receptor (LBR) transcriptional upregulation correlates with melanoma progression and NE fragility." (PMID 41706894, 2026). "Additionally, we found LMNB1 and LBR to be downregulated in the melanocytic BRAFV600E senescence model as well as in etoposide-induced senescence model in melanoma cells." (PMID 35883595, 2022). "It became clear by our results that changes in the chromatin structure like the development of heterochromatin foci or influence on chromatin condensation are dependent on LMNB1 and the LBR in melanoma and a constant downregulation by long term treatment leads to structural and functional changes." (PMID 35883595, 2022). "The increased amount of heterochromatin foci in LBR-knockdown cells indicates that the LBR might have similar functional effects as LMNB1 in melanoma." (PMID 35883595, 2022). "In summary, we could not only show that knockdown of LMNB1 or LBR in melanoma cells leads to senescence but also vice versa, LMNB1 and LBR are significantly downregulated in our senescent models supporting a function in regulation of senescence." (PMID 35883595, 2022). "p < 0.1) upregulation of the LBR in melanoma cell lines and tissues." (PMID 35883595, 2022).
melanoma (continued). "Our analysis newly revealed that a downregulation of LMNB1 and the LBR might regulate mitotic processes and based on defects in replication, lead to cellular senescence and changes in chromatin state in malignant melanoma." (PMID 35883595, 2022). "Therefore, in this study, we address the functional role of LMNB1 and the LBR in melanoma." (PMID 35883595, 2022). "Therefore, we hypothesize that a robust long-lasting LMNB1 or LBR downregulation is necessary to create a strong chromatin change and consequently a senescence phenotype in melanoma." (PMID 35883595, 2022). "The role of LMNA is well studied in melanoma, however the role of LMNB1 and the corresponding receptor LBR remained unclear so far." (PMID 35883595, 2022). "For defining the molecular function of the LBR in melanoma, we first evaluated the gene expression in the RNA-Seq data of different melanoma cell lines compared to NHEMs (PRJNA839865) and in the primary melanoma compared to melanocytic nevi (GSE112509)." (PMID 35883595, 2022). "Conclusively, melanoma cells express high levels of LMNB1 and LBR to prevent senescence." (PMID 35883595, 2022). "In this study, we could show that melanoma needs LMNB1 and the LBR for translational processes." (PMID 35883595, 2022).
cervical cancer (1 paper, 2022). A primary or metastatic malignant neoplasm involving the cervix. "The LBR was also reported to be mislocalized and downregulated in senescence induced cervical cancer cells by the protease inhibitor MG132 and therefore might play a key role in cellular senescence." (PMID 35883595, 2022).
chondrodysplasia (1 paper, 2018). "Recessive loss-of-function mutations in the lamin B receptor (LBR) and the thyroid hormone receptor interactor 11 (TRIP11) genes cause lethal human chondrodysplasias with distinct phenotypes." (PMID 30518689, 2018). "Recessive loss-of-function mutations of LBR are known to cause GRBGD, a prenatally lethal chondrodysplasia with recognizable radiographic features." (PMID 30518689, 2018).
colon cancer (1 paper, 2018). "Six genes (aldehyde dehydrogenase 2, neural precursor cell expressed, developmentally down-regulated 9, filamin A, lamin B receptor, twinfilin actin binding protein 1, serine and arginine rich splicing factor 1) were closely related to the OS of colon cancer patients." (PMID 30155352, 2018). "However, no study has yet reported the role of LBR and TWF1 in CRC and therefore their role needs be investigated further in colon cancers." (PMID 30155352, 2018).
COVID-19 (1 paper, 2021). A disease caused by infection with severe acute respiratory syndrome coronavirus 2. "Of note, we found that acute- and post-COVID-19 monocytes had a higher accessibility in the promoter region of lamin-B receptor (LBR), a gene related to protection against cellular senescence." (PMID 34572439, 2021).
depression (1 paper, 2025). "Six potential depression‐related target genes of miR‐511‐3p were identified: CXCR4, LBR, CPS1, VPS13B, COL9A3, and GABRB3." (PMID 41341504, 2025).
developmental delay (1 paper, 2025). "Recessive variants in TMEM147, a gene involved in anchoring lamin B receptor (LBR) and with downstream effect on ER homeostasis, were found in patients with coarse facies, developmental delay, intellectual disability, and behavioral problems." (PMID 39420677, 2025).
glioma (1 paper, 2022). A benign or malignant brain and spinal cord tumor that arises from glial cells (astrocytes, oligodendrocytes, ependymal cells). "The RT-qPCR assay showed that the six signature genes (TRIM24, IDH1, LBR, HMG20B, USP49, and RCC1) were up-regulated in glioma cell lines in mRNA expression level." (PMID 36246611, 2022). "Our study suggests that TRIM24, IDH1, LBR, HMG20B, USP49 and RCC1 were all highly expressed in glioma tissues and gliomar cell lines both at the mRNA and protein level." (PMID 36246611, 2022).
Hemivertebrae (1 paper, 2025). Absence of one half of the vertebral body. "This case report describes a novel LBR mutation identified in a child presenting with PHA and hemivertebrae, further expanding the known phenotypic spectrum associated with LBR mutations." (PMID 40980134, 2025). "Notably, the patient exhibited scoliosis secondary to hemivertebrae, potentially representing a previously unreported skeletal manifestation of mutations in the LBR gene." (PMID 40980134, 2025).
Hutchinson-Gilford progeria syndrome (1 paper, 2025). "Mutant lamin A/C is associated with Hutchinson-Gilford Progeria Syndrome (HGPS), which shows similar hallmarks of impaired keratinocyte differentiation and upregulated LBR expression." (PMID 39943681, 2025).
invasive breast carcinoma (1 paper, 2025). A carcinoma that infiltrates the breast parenchyma. "Lower lamin A/C and lamin B1 expression; decreased levels of emerin in invasive breast cancer; downregulation of SUN1, SUN2, and nesprin‐2; upregulation of LBR." (PMID 39866838, 2025).